CRP (C-reactive protein)
Diseases named in the same sentence as CRP in open-access papers (continued):
Sharing a sentence is not in itself a finding about the gene and the disease.
coronary artery disease (continued). "In patients with stable coronary disease, plasma APR proteins CRP, IL-1 receptor antagonist, and fibrinogen γ decrease after apabetalone treatment versus placebo, resulting in a predicted downregulation of the APR pathway and cytokine targets." (PMID 32821285, 2020). "Optimal coronary artery disease (CAD) therapy was commenced, and Behcet's disease treatment was intensified with the normalization of C-reactive protein." (PMID 31602349, 2019). "A recent study has shown that ccf-mtDNA was elevated in type 2 diabetes patients with coronary heart disease (CHD) and correlated with C-reactive protein (CRP) levels." (PMID 30965677, 2019). "More importantly, reduction of C-reactive protein and aCL levels after treatment with ASA has been described in patients with coronary artery disease, a finding attributed to a reduction of antigen load." (PMID 30210500, 2018). "In relation to the cardiovascular system, elevated CRP is a marker for decreased LVEF and diastolic dysfunction in the context of coronary artery disease, myocardial infarction and congestive heart failure." (PMID 29534446, 2018). "In patients with coronary artery disease undergoing all types of PCI, baseline CRP level predicts one-year mortality and MACE15, 22, result which is concordant with our findings." (PMID 28128312, 2017). "For instance, C-reactive protein (CRP) is a prototypic marker of inflammation which is elevated in many CVD such as acute myocardial infraction, coronary artery disease and HT [13••, 16]." (PMID 28360962, 2017). "As compared with controls, all patients with coronary heart disease (including SA and ACS) have higher levels of hs-CRP and resistin, but lower levels of adiponectin." (PMID 26986475, 2016). "Statistical analysis revealed that history of coronary artery diseases, NIHSS score, statin therapy, platelet count, serum LDL-cholesterol, hs-CRP and serial Ox-LDL levels were significantly different between the good- and poor-outcome groups." (PMID 24423248, 2014). "In large population based case–control studies, as in large COPD cohorts levels of CRP are demonstrably higher in stable COPD patients than in controls after adjusting for the confounding factors: sex, age, tobacco consumption and ischemic heart disease." (PMID 25425298, 2014). "We analysed the link between CIMT and hs-CRP in cases with coronary artery disease (CAD)." (PMID 24217304, 2013). "Statin drug therapy may lower the risk of coronary artery disease and provide vascular protection not only by reducing the level of LDL-C but also by targeting and reducing the level of circulating atherogenic L5, which in turn lowers circulating CRP levels and local endothelial CRP expression." (PMID 23950953, 2013). "For example, assuming that elevated levels of CRP is not a contributing causal factor for coronary heart disease, then genetic variants which index CRP, should not be related to coronary heart disease, even though levels of CRP may serve as a useful biomarker of disease risk." (PMID 24204319, 2013). "In clinical studies, the levels of high sensitivity C-reactive protein (hs-CRP) and interleukin-6 (IL-6) are commonly used as inflammatory markers that contribute the early stages of coronary artery disease." (PMID 23029185, 2012). "Although the IL6R rs7529229 variant was associated with reduced circulating C-reactive protein and fibrinogen concentrations, this study should not be interpreted as a mendelian randomisation analysis investigating causality of C-reactive protein or fibrinogen in coronary heart disease." (PMID 22421340, 2012). "Elevated CRP paralleling ECG changes, including QT prolongation and decreased T-wave amplitude, has also been reported in coronary artery disease patients exposed to ambient fine PM." (PMID 19479011, 2009). "CAD: Coronary artery disease; CAR: C-reactive protein-to-albumin ratio." (PMID 40922854, 2025).
coronary artery disease (continued). "Since the routine usage of CRP as a prognostic factor of coronary artery disease (CAD) is not clear, it is still an unmet clinical need to find prognostic predictors in high-risk patients with CAD." (PMID 40747494, 2025). "In a 12-month randomized, open-label, prospective trial of 51 subjects with T2DM, empagliflozin yielded a 54% reduction in hs-CRP compared with placebo, and a 6-month intervention in patients with T2DM with coronary artery disease also reported a significant decrease in CRP." (PMID 40149704, 2025). "This association persists after comprehensive adjustment for insulin resistance, inflammatory markers including C-reactive protein and interleukin-6, natriuretic peptides such as BNP/NT-proBNP, and comorbidities like coronary artery disease or diabetes mellitus." (PMID 41347124, 2025). "The CRP is higher in non-diabetic subjects with coronary heart disease than in people with diabetes, and PON1 is the most reduced, but further investigations are needed to assess if those are the best markers." (PMID 38474211, 2024). "CRP also slightly increases in coronary heart disease, so, it is not a specific marker involved in SLE." (PMID 39702549, 2024). "Nevertheless, for both sexes, AIP showed higher correlations with CRP than CRI-I, which could be related to the fact that AIP has been reported as a better predictor of coronary artery disease than CRI-I and other atherogenic indices." (PMID 39338158, 2024). "CRP, a marker of systemic inflammation, also correlated significantly with CAD severity, peaking in TVD patients (4.0 ± 0.9 mg/L), suggesting an inflammatory component in more advanced coronary disease." (PMID 39463905, 2024). "This supports that CRP does not appear to contribute to the increase in ischemic heart disease in women with SCH." (PMID 39687453, 2024). "Notably, patients with acute coronary syndrome have higher erythrocyte-FC than do those with stable coronary artery disease, and erythrocyte-FC content better predicted acute coronary syndrome than either HDL-C or C-reactive protein levels." (PMID 37821077, 2023). "SII was found to be a better predictor of coronary artery disease than PLR, NLR, and CRP." (PMID 36769776, 2023). "In the context of coexisting periodontitis and coronary artery disease, non-surgical mechanical periodontal approach decreased the levels of hs C-reactive protein, fibrinogen and white blood cells." (PMID 39077523, 2023). "The top 5 clusters of keywords co-occurrence are inflammation, C-reactive protein, coronary heart disease, nonsteroidal anti-inflammatory, and myocardial infarction." (PMID 36873405, 2023). "In MR models for the effect of CRP, triglycerides, and HDL-cholesterol on coronary artery disease, violations of the instrumental conditions were detected by the instrumental inequalities, MR-Egger, and by MR-PRESSO when proposing all SNPs jointly as instruments." (PMID 37253997, 2023). "Cytomegalovirus (CMV); chronic obstructive pulmonary disease (COPD); ischemic heart disease (IHD); atrial fibrillation (AF); chronic kidney disease (CKD), C-reactive protein (CRP), neutrophil/lymphocyte ratio (NLR); clinical frailty scale (CSF); and interquartile range (IQR)." (PMID 37047803, 2023). "We found that there were statistically significant differences between Group 1 and Group 4 in age, diastolic BP, BMI, NYHA class, coronary artery disease, lg BNP, WBC, RBC, NBC, LBC, NLR, CRP, Hb, sodium, potassium, chlorine, Alb, Cre, UA, TC, eGFR, QRS wave, LAd, LVDd, and LVEF (p < 0.05)." (PMID 37978441, 2023). "Since inflammation is thought to play a significant role in the etiology of coronary artery disease, the levels of inflammatory biomarkers, such as IL-6, CD40,c-reactive protein (CRP), complement, and myeloperoxidase (MPO), can be used to gauge the severity and prognosis of coronary artery disease." (PMID 38084332, 2023).
coronary artery disease (continued). "The strongest keywords were “coronary heart disease (20.73),” and most recently “heart failure (18.28), nonsteroidal anti-inflammatory drug (NSAIDs) (17.51), oxidative stress (16.62), c reactive protein (12.18), and tumor necrosis factor (10.36)." (PMID 36873405, 2023). "The strongest keywords were “coronary heart disease (20.73),” and most recently “heart failure (18.28),” nonsteroidal anti-inflammatory drug (17.51), oxidative stress (16.62), c reactive protein (12.18), tumor necrosis factor (10.36)." (PMID 36873405, 2023). "Although CRP is a nonspecific marker of inflammation, it is predictive of coronary heart disease and gastrointestinal diseases." (PMID 36005503, 2022). "In male patients (76.2%), ischemic heart disease, chronic kidney disease, and cerebrovascular disease, low lymphocyte count, low albumin, high LDH, high ferritin, high C-reactive protein (CRP), high procalcitonin, and high D-dimer were considered as the high-risk factors for critical illness." (PMID 35685537, 2022). "As an inflammatory marker, hs-CRP can be useful in the acute setting to rule out significant coronary artery disease (CAD), and it should be combined with other imaging modalities to enhance its sensitivity." (PMID 35621834, 2022). "This is in line with previous studies showing that higher CRP levels in non-O patients were also found in other conditions, such as ischemic heart disease." (PMID 36614946, 2022). "In addition, PCSK9 levels are associated with a higher plasma concentration of fibrinogen (r = 0.211, p = 0.002) and C reactive protein (CRP) (r = 0.153, p = 0.023) in patients with coronary artery disease (CAD)." (PMID 35683632, 2022). "There was a decline in CRP in WENBIT, which may be related to lipid-lowering treatment in coronary artery disease, thus concealing the natural course of CRP." (PMID 36312896, 2022). "Coronary artery spasm (CAS), an inflammatory nonobstructive coronary disease characterized by elevated C-reactive protein (CRP) levels, plays an important role in myocardial ischemia, infarction, and sudden death 1,2." (PMID 34104095, 2021). "Patients with coronary heart disease with or without periodontitis presented higher levels of CRP than those of healthy individuals." (PMID 33603787, 2021). "Given the considerations above, we hypothesized that CRP levels might provide clinical and prognostic information that is unique in MINOCA and at difference to myocardial infarction with significant coronary artery disease (MI‐CAD)." (PMID 34032303, 2021). "Furthermore, exercise induces a reduction in C-reactive protein (CRP), IL-1, IL-6, interferon-γ (INF-γ) levels in coronary artery disease patients, demonstrating its anti-inflammatory effects." (PMID 34489641, 2021). "Further, in patients with non-obstructive coronary artery disease, high sensitivity C-reactive protein (hs-CRP) correlates with both angina as well as markers of ischemia." (PMID 33806050, 2021). "CRP, a major inflammatory biomarker, is associated with higher IMT and ischemic stroke, carotid atherosclerosis, or coronary heart disease, although this association has not been confirmed in some studies." (PMID 32214403, 2020). "GDF-15 and NT-proBNP predicted CLT in unadjusted model, after adjustment for age, sex, BMI and fibrinogen as well as after additional adjustment for coronary artery disease, heart failure/left ventricular dysfunction, GFR, antiplasmin, PAI-1, TAFI, CRP, cTnI-hs." (PMID 31280356, 2020). "In univariable Cox proportional hazard analysis, age, gender (male), ischemic heart disease, atrial fibrillation, MBP, hemoglobin, eGFR, sodium, blood urea nitrogen, log CRP, log BNP, history of HF, diuretics, log GNRI and log TCBI were associated with the all-cause mortality." (PMID 33137941, 2020). "As a well-known inflammatory biomarker, hs-CRP is significantly elevated in patients dying suddenly with severe coronary artery diseases, both with and without acute coronary thrombosis." (PMID 31694563, 2019).
coronary artery disease (continued). "Multivariable linear regression demonstrated that older age, non‐ischemic heart disease, increased urea, low hemoglobin and sodium, non‐treatment with ACE‐I/ARB and thiazide, low iron and increased CRP were predictive of low serum albumin (R2 = 0.278, P < 0.0001, Table SS1)." (PMID 30637771, 2019). "In a study of 7,735 cases of fatal and non-fatal coronary heart disease, C-reactive protein (CRP), serum amyloid A protein (SAA), and serum albumin were found to be associating factors with an increased risk of heart disease." (PMID 28326084, 2017). "However, in coronary artery disease the correlation between ALP and C-reactive protein level was minimal." (PMID 28182682, 2017). "It is noteworthy that the concentration of CRP, IL-6 and TNF observed in this study appeared to be slightly larger than the values found in Chinese patients with type 2 diabetes or coronary heart disease and in the prospective Multi-Ethnic Study of Atherosclerosis." (PMID 26080804, 2015). "For example, C-reactive protein (CRP), an inflammatory risk factor of endothelial dysfunction, is associated with fatal and non-fatal coronary artery disease (CAD) events in a healthy population." (PMID 25512264, 2014). "Previous studies have investigated the relationship between CRP and Framingham coronary heart disease scores in subjects without clinical cardiovascular disease." (PMID 23587204, 2013). "High-sensitivity C-reactive protein (hs-CRP) is a non-specific marker of inflammation that has been shown to have prognostic significance in patients with coronary artery disease." (PMID 21702934, 2011). "The available evidence supports a negative recommendation, i.e., that CRP should not be routinely measured among patients with stable coronary disease to quantify prognosis or to guide interventional therapies." (PMID 20532236, 2010). "The quality of published evidence on CRP and prognosis in stable coronary disease is poor and is not sufficient to recommend routine measurement of this biomarker." (PMID 20532236, 2010). "A positive correlation of C-reactive protein (CRP) and coronary artery disease, which could be explained by the atherogenic effects of chronic inflammation, is well known." (PMID 16263508, 2005). "Notably, Kuller found that WBC count, but not CRP level, was an independent predictor of death in men with MetS and coronary heart disease." (PMID 39011047, 2024). "In addition, PCSK9 inhibitors did not change high sensitivity C-reactive protein (CRP) levels in the patients with coronary artery disease." (PMID 39149582, 2024). "Moreover, each unit increase in hs-CRP was associated with a 0.54 increase in PHQ-9 score (β=0.68, 95% CI=0.26-1.11) in participants with coronary artery disease than in those without coronary artery disease (β=0.14, 95% CI=0.04-0.23)." (PMID 38596631, 2024). "We did not perform definitive testing for microvascular coronary artery disease (scuh as coronary blood flow reserve with coronarography) and we also did not test for sensitive markers of inflammation, for example, high-sensitivity C-reactive protein." (PMID 37710152, 2023). "In coronary artery disease this medicament decreases IL-6 level, increases TGF-β and IL-22, while in acute myocardial infarction it decreases IL-6, TNF-alfa, and C reactive protein (CRP), which in both cases should lead to alleviation of inflammation-related complications." (PMID 35163696, 2022). "The negative correlation of T with both CRP and the values of the SYNTAX score in the current study indicated a significant association of T with coronary disease severity, presence of acute coronary thrombosis, and, thus, deteriorated left ventricular systolic function." (PMID 36199650, 2022). "However, the patients in these RCTs had low baseline CRP levels and did not have unstable coronary artery disease." (PMID 36568547, 2022).
coronary artery disease (continued). "Increased C-reactive protein (CRP) levels have been observed in TAA, with respect to coronary artery disease patients and healthy controls, which may reflect the extensive inflammatory reaction and severe coagulopathies in individuals with acute type A aortic dissection and thoracic aortic aneurysm." (PMID 35892496, 2022). "With regard to The Low Dose Colchicine after Myocardial Infarction (LoDoCo-MI) study, it was found that the administration of low dose colchicine did not contribute to the reduction of hs-CRP which is independent of aspirin and statin in patients with coronary artery disease." (PMID 34876021, 2021). "However, there has been no study about the relation of two critical factors in ischemic heart disease: serum CRP and myocardial miRNAs." (PMID 31063484, 2019). "The high hs-CRP/PAB ratio group had a higher proportion of diabetics and patients with known coronary artery disease (CAD)." (PMID 31399624, 2019). "However, some epidemiological studies failed to support the notion that the common variation in CRP gene had an alternative effect on the occurrence of coronary heart diseases." (PMID 29951057, 2018). "For example, Martinelli and colleagues examined associations among 13 FADS genotypes, desaturase activity (as determined by ARA/LA ratios), inflammation (C-reactive protein (CRP)), and coronary artery disease (CAD) in 876 individuals with (n = 610) and without (n = 266) CAD." (PMID 29068398, 2017). "However, after adjustment for heterogeneity, neither GRS showed a significant effect of CRP level (at p < 0.0016) on any of these outcomes, including coronary artery disease, nor on the other 20 complex outcomes studied." (PMID 27327646, 2016). "Studies stated serum concentration of CRP (C-reactive protein) has the most consistent relation with coronary artery disease, so that it could be considered as a nontraditional cardiovascular risk factor." (PMID 25901155, 2015). "In addition, smoking and inflammation (detected by a high CRP level) have been reported to have a more negative influence on coronary artery disease in women than in men." (PMID 24624968, 2014). "Similarly to the results of the current study, meta-analysis of prospective studies showed a positive correlation between coronary heart disease and fibrinogen, C-reactive protein, and leukocyte counts, and a negative correlation with albumin." (PMID 21822486, 2012). "Later, several clinical studies extended these results to cohorts without manifest CVD by demonstrating that also among subjects with no prior occurrence of ischemic heart disease, plasma CRP levels serve as a prognostic marker for future cardiovascular events." (PMID 19578488, 2008). "More recent studies have shifted the point of view about relationship between CRP and coronary artery disease because they have clearly indicated that CRP might be no more considered not only a simple marker of disease but it is actively involved in acute coronary syndrome (ACS) pathophysiology." (PMID 36768804, 2023). "There was significant difference in serum CRP level between the coronary artery disease (CAD) group and the non-CAD group." (PMID 34900087, 2021). "CRP is a protein secreted by the liver that reflects inflammation and is strongly predictive of CVD outcomes, such as with coronary heart disease (CHD), ischemic stroke, vascular mortality, and non-vascular mortality or CVD mortality." (PMID 35807807, 2022). "Concentrations of C-reactive protein (CRP), serum amyloid A, and interleukin-6 were increased in patients with coronary heart disease but failed to correlate with acuteness of coronary disease." (PMID 19662190, 2007). "Furthermore, ESR, CRP and platelet levels were high in a comparable percentage of those with CAA and those without, thus they are not predictive of coronary disease, as already seen." (PMID 31493782, 2019).